MIR3127 (microRNA 3127)
Synonyms: hsa-mir-3127; mir-3127
Gene: MicroRNA gene on chromosome 2 (96,798,278 to 96,798,353, forward strand). Ensembl gene ENSG00000264157.
Homologues: Orthologues: chimpanzee MIR3127 (100% identical).